TRPA1 (transient receptor potential cation channel subfamily A member 1)
Diseases named in the same sentence as TRPA1 in open-access papers (continued):
Sharing a sentence is not in itself a finding about the gene and the disease.
tumor (continued). "Notably, tumor metastasis in the skeleton has been reported to induce significant bone remodeling and tissue damage that leads to the release of BK and indirect sensitization of TRPV1 and TRPA1 channels or direct activation of TRPA1 channels." (PMID 35053150, 2021). "Notably, most of the tumor cells infiltrating the brain lack TRPA1 expression unlike tumor cells in primary LUAD tissues." (PMID 29038531, 2017). "This in turn raises an interesting question of whether formaldehyde at pathologically low concentrations (1∼3 mM, based on the concentrations of formaldehyde detected in human tumor tissues) can induce pain responses, and whether TRPV1 or TRPA1 is involved in the pain responses." (PMID 20422007, 2010). "However, TRPA1 also resulted in being expressed in a subset of cases negative with pS100, SOX10 and/or SNAIL and SLUG, and we may speculate that these divergent phenotypes could reflect a process of tumor plasticity and dedifferentiation of neural-derived SSs." (PMID 33076385, 2020). "Tumor colon biopsies, used for comparison in the present study, express TRPV1 and TRPA1 local mRNA gene expression but do not exhibit significant change in their gene expression levels compared to non-inflamed controls." (PMID 25265225, 2014). "Surrounding tumour nests, we found distinct peritumoral stromal regions positive for POSTN/α-SMA (i.e., myoCAFs) that did not appear to express GSN, and sub-populations expressing TRPA1." (PMID 40640495, 2025). "TRPA1, originally named p120, was first cloned from fibroblasts by Jaquemar and colleagues when a novel mRNA was discovered in fibroblasts but was completely absent in SV40-transformed cells and mesenchymal tumor cell lines." (PMID 26149285, 2016). "TRPA1 positivity was also observed in a subset of cases negative with pS100, SOX10 and/or SLUG/SNAIL, and these divergent phenotypes may reflect a process of tumor plasticity and dedifferentiation of neural-derived SSs." (PMID 33076385, 2020).
inflammation (29 papers, 2015 to 2025). Aberrant reaction of the microcirculation characterized by movement of fluid and leukocytes from the blood into extravascular tissues. "Our results demonstrated that cold air exposure significantly exacerbated eosinophilic airway inflammation in a papain-treated murine model, and this inflammation was ameliorated in Trpa1 KO mice or WT mice treated with a TRPA1 channel antagonist." (PMID 41322401, 2025). "Our findings highlight that TRPA1 functions not only in sensory neurons but also in airway epithelial cells, underscoring the novelty of epithelial TRPA1 as a contributor to cold-induced airway inflammation." (PMID 41322401, 2025). "TRPA1 has been shown to promote leukocyte infiltration to the lung, including neutrophils in models of airway inflammation." (PMID 37386145, 2023). "The aim of this study was to determine the TRPA1-targeted effects of PR against pulmonary inflammation and to investigate the affinity of PR constituents for TRPA1 and their potential mechanisms of action." (PMID 37446875, 2023). "TRPA1 is an ion channel that functions as a sensor for an array of environmental and endogenous irritants to mediate pain and neurogenic inflammation; pinosylvin was found to inhibit TRPA1-mediated Ca2+ influx in vitro and acute paw inflammation in mice." (PMID 34066748, 2021). "We recently reported that TRPA1 is expressed in lung epithelial cells (LECs) and mediates lung inflammation induced by cigarette smoke." (PMID 33281629, 2020). "We investigated its involvement in acute and chronic pulmonary inflammation using Trpa1 gene-deleted (Trpa1−/−) mice." (PMID 32526913, 2020). "It is highly probable that TRPV1 and TRPA1 will be activated simultaneously during episodes of airway inflammation." (PMID 31170994, 2019). "Macrophages, the other key players of CFA-evoked joint inflammation, also express TRPA1 mediating anti-inflammatory effects." (PMID 26746673, 2016). "Thirdly, we wanted to assess the importance of lung epithelial TRPA1 to CS-induced lung inflammation using a murine model that consisted of chronic CS exposure for 4 weeks." (PMID 26504357, 2015). "To investigate the role of lung epithelial TRPA1 in vivo, we employed an established murine lung inflammation model involving induction by chronic CS exposure for 4 weeks." (PMID 26504357, 2015). "TRPA1 is a non-selective cation channel, activation of which causes pain and neurogenic inflammation." (PMID 36698198, 2023). "Both TRPV1 and TRPA1, members of the TRP channel superfamily, play a key part in lung inflammation via the release of neuropeptides (substance P) and proinflammatory factors, such as leukotriene, IL-1α, and TNF-α, which cause primary airway inflammation." (PMID 37836429, 2023). "Moreover, the enhanced activity of TRPA1 in TG neurons evoked by TMJ inflammation or masseter muscle injury was suppressed by inhibition of TMEM100." (PMID 37033371, 2023). "Previous studies have demonstrated that TRPA1 is a mediator of lung inflammation." (PMID 35805655, 2022). "Similar to its role in dermal inflammation, TRPA1 plays a key role in pulmonary inflammation." (PMID 33193423, 2020). "Transient receptor potential (TRP) vanilloid 1 (TRPV1) and ankyrin 1 (TRPA1) both may play important roles in lung inflammation and AHR." (PMID 31281589, 2019). "This could further influence the feasibility of targeting TRPA1 in lung inflammation." (PMID 37386145, 2023). "Thus, lung epithelial TRPA1 may detect the presence of LPS and transduce this information into the transcriptional regulation of lung inflammation via a Ca2+-dependent signaling pathway." (PMID 33281629, 2020). "Although either TRPV1 or TRPA1 activation causes neurogenic airway inflammation, an additional inflammatory response which is not neurogenic is solely orchestrated by TRPA1 activation, suggesting that non-neuronal TRPA1 in the airways likely contributes to inflammatory airway diseases." (PMID 25897313, 2015).
inflammation (continued). "However, the role of TRPA1 in LPS-induced lung inflammation has not been conclusively defined, and its underlying cellular mechanisms remain unclear." (PMID 33281629, 2020). "Unlike its role in dermal and pulmonary inflammation, TRPA1 has been found to have contradictory pro- and anti-inflammatory roles in gastrointestinal inflammation." (PMID 33193423, 2020). "Although non-neuronal activation of TRPA1 was reported in airway inflammation, other TRPA1 functions in non-neuronal tissues remain elusive." (PMID 30717260, 2019). "Importantly, early administration of a TRPA1 or a TRPV1 antagonist attenuated the transition and development of experimental pancreatic inflammation and pain from acute experimental to chronic, thereby providing an effective disease-modifying therapy." (PMID 30388732, 2018). "The overall effect of DEP is neurogenic inflammation through release of substance P and neurokinin A (mediated by TRPA1 and TRPV1) and through production of cytokines and chemokines (mediated by TRPV1 and TRPM8), and variations in TRPA1 activation promote differences in lung inflammation and injury." (PMID 33803491, 2021). "Here, we show that luteolin antagonized the Ca2+ elevation response to icilin in TRPM8-HEK293 cells, without activating or inhibiting TRPV1- or TRPA1, the main TRP channels involved in gut inflammation." (PMID 40280909, 2025).
peripheral neuropathy (20 papers, 2012 to 2025). A disorder affecting the peripheral nervous system. "In summary, these data indicate that DJ-1 is linked to TRPA1 expression and activity, controlling both the development of cold hypersensitivity and peripheral neuropathy." (PMID 39486088, 2025). "Recent evidence suggests that TRPA1 is implicated in developing chemotherapeutic-induced peripheral neuropathy (CIPN), mediating the mechanical and cold hypersensitivity provoked by platinum-based anticancer drugs." (PMID 38564162, 2024). "Nox4 has also been implicated in chemotherapy-induced peripheral neuropathy, because the downregulation of Nox4 suppressed the upregulation of TRPA1 in the spinal cord in a model of oxaliplatin-induced peripheral neuropathy." (PMID 35740059, 2022). "The TRPA1 c.1954C>T variant has been seen before in a German painful-diabetic-peripheral-neuropathy patient." (PMID 36430572, 2022). "Among the many studies seeking to explain the underlying mechanism of peripheral neuropathy, one demonstrated a mechanical change involving the calcium-permeable cation channel TRPA1." (PMID 25928068, 2015). "Based on this, we hypothesised that activation of the kinin B2 receptor and its underlying pathways could contribute to TRPA1 sensitisation in the model of painful peripheral neuropathy induced by cisplatin." (PMID 37513871, 2023). "Of note, similar to our observations here, painful peripheral neuropathy in response to the chemotherapy agent vinblastine also requires TrpA1 both in flies and mice, suggesting that the underlying mechanism of sensitization in response to different injuries may show some conservation." (PMID 31309148, 2019). "In hindlimb ischemia and peripheral neuropathy, as experimental models of PAD, spontaneous pain-associated behavior during reperfusion was decreased following TRPA1 genetic ablation and pharmacological inhibition." (PMID 38333756, 2024). "In this context, using a model of painful peripheral neuropathy induced by cisplatin in mice, we present evidence of the functional interaction between the kinin B2 receptor and the TRPA1 channel and its contribution to cisplatin-induced painful symptoms." (PMID 37513871, 2023). "Although its pathophysiology is poorly understood, it is known that kinin receptors and the transient receptor potential ankyrin 1 (TRPA1) channel play a significant role in the peripheral neuropathy induced by cisplatin in rodents." (PMID 37513871, 2023). "We assessed the role of kinin B2 and B1 receptors and the TRPA1 channel on cisplatin-induced peripheral neuropathy using pharmacological approaches." (PMID 37513871, 2023). "To elucidate the role of TRPA1 activation in carboplatin-induced peripheral neuropathy, we examined the effects of a TRPA1 inhibitor on both mechanical allodynia and cold hyperalgesia induced by carboplatin." (PMID 31277262, 2019). "To clarify how TRPA1 is related to carboplatin-induced peripheral neuropathy, we first investigated the amount of TRPA1 protein in the DRG of model mice." (PMID 31277262, 2019). "Oxaliplatin, a third-generation platinum-based chemotherapeutic agent, displays unique acute peripheral neuropathy triggered or enhanced by cold, and accumulating evidence suggests that transient receptor potential ankyrin 1 (TRPA1) is responsible." (PMID 29163216, 2017). "In the present study, we demonstrated that Al accumulation augments the peripheral neuropathy induced by oxaliplatin through activation of TRPA1 and induction of cell death in the DRG." (PMID 25928068, 2015). "A useful marker for research into peripheral neuropathy, Transient Receptor Potential Ankyrin-1 (TRPA1), is activated by adversely cold temperatures." (PMID 25928068, 2015). "In the present study, behavioral test results for the peripheral neuropathy induced by infusion of aluminum chloride and oxaliplatin, each alone or both in combination, correlated with the activation of TRPA1 mRNA and protein expression." (PMID 25928068, 2015).
peripheral neuropathy (continued). "In the present study, we demonstrated for the first time in vivo that Al accumulation augments the peripheral neuropathy induced by oxaliplatin through activation of TRPA1 and induction of cell death in the DRG." (PMID 25928068, 2015). "The purpose of this study was to reveal the synergistic effect of Al accumulation on oxaliplatin-induced peripheral neuropathy by activation of TRPA1." (PMID 25928068, 2015). "In the present study, we provide the first evidence that TRPA1 in DRG neurons mediates the acute phase of oxaliplatin-induced peripheral neuropathy, as supported by the following results." (PMID 22839205, 2012). "Although the exact mechanisms of TRPA1 remain unclear, our findings and prior studies indicate its involvement in mechanical hypersensitivity in various peripheral neuropathies." (PMID 39486088, 2025). "Lastly, we elucidated that the intracellular signalling pathways, phospholipase C (PLC) and protein kinase C epsilon (PKCε), downstream from kinin B2 receptor activation are critical to sensitising the TRPA1 channel in the cisplatin-induced peripheral neuropathy model in mice." (PMID 37513871, 2023). "In this context, we supposed that activating the kinin B2 receptor could be essential to sensitising the TRPA1 channel in the cisplatin-induced peripheral neuropathy model." (PMID 37513871, 2023). "L-OHP-induced acute peripheral neuropathy is associated with calcium channels, such as TRPM8 and TRPA1, and sodium channels in the dorsal root ganglion (DRG), whereas chronic peripheral neuropathy is correlated with damage to nerve and ganglion cells by L-OHP accumulation." (PMID 37069612, 2023). "Hereafter, we evaluated whether signalling pathways downstream from the kinin B2 receptor activation could cooperate with TRPA1 channel activation in cisplatin-induced peripheral neuropathy." (PMID 37513871, 2023). "Therefore, regulating the activation of signalling pathways downstream from the kinin B2 receptors activation and TRPA1 channel sensitisation can mitigate the painful peripheral neuropathy decurrent of the oncology treatment with cisplatin." (PMID 37513871, 2023). "Therefore, our results suggest crosstalk between the kinin B2 receptor (and partial of B1 receptor) and TRPA1 channel in nociceptive transmission in this peripheral neuropathy model." (PMID 37513871, 2023). "However, the role of TRPA1 in carboplatin-induced peripheral neuropathy is unclear." (PMID 31277262, 2019). "We investigated the effects of an AKAP inhibitor on TRPA1 activation in hTRPA1-expressing HEK293 cells, particularly on mechanical allodynia and cold hyperalgesia in carboplatin-induced peripheral neuropathy." (PMID 31277262, 2019). "We analyzed the effects of an TRPA1 inhibitor on carboplatin-induced pain behavior, and measured the level of TRPA1 protein in DRG using carboplatin-induced peripheral neuropathy model mice." (PMID 31277262, 2019). "In the PTX-induced peripheral neuropathy (PIPN) model, the TRPA1 channel is regulated by PKA and/or PKC phosphorylation through PAR2 cleavage and activation; the latter is mediated by the release of tryptase, which ends in CIPN and is characterized by mechanical, heat, and cold hypersensitivity." (PMID 36098890, 2023). "In this test, TRPA1 antagonist HC-030031 demonstrated no statistically significant antiallodynic properties in both phases of oxaliplatin-induced peripheral neuropathy, administered at doses 1.5 and 10 mg/kg." (PMID 35930193, 2022). "In this study, we used a mouse model to investigate whether TRPA1, TRPM8, and TRPV1 are involved in the oxaliplatin-induced acute peripheral neuropathy." (PMID 22839205, 2012). "Peripheral neuropathy in Dj-1−/− mice was also reversed in mice lacking TRPA1." (PMID 39486088, 2025). "However, the signalling pathways that activate TRPA1 downstream of kinin receptors activation have not yet been elucidated in cisplatin-induced peripheral neuropathy." (PMID 37513871, 2023).
peripheral neuropathy (continued). "Furthermore, the TRPA1 channel sensitisation through the kinin B2 receptor activation via PLC and PKCε seems involved in mechanical and cold hypersensitivity in the cisplatin-induced peripheral neuropathy model." (PMID 37513871, 2023).
respiratory diseases (17 papers, 2015 to 2024). "Over the years, studies have linked TRPA1 to various physiological and pathological processes, including neurogenic inflammation, respiratory diseases, and chronic pain conditions." (PMID 39022308, 2024). "Additionally, TRPA1 activation associated with particulate matter, a rapidly growing problem, may have implications for respiratory diseases." (PMID 39273183, 2024). "TRPA1 dysregulation and respiratory pathophysiology, offer insights into potential therapeutic interventions for the management of respiratory disorders." (PMID 39022308, 2024). "TRPA1 is a transmembrane cation channel, one of the most promising targets in the context of respiratory diseases." (PMID 35630553, 2022). "TRPA1 plays an important role in respiratory diseases, and most compounds that induce cough can activate the TRPA1 channel." (PMID 35911969, 2022). "Currently, TRPA1 inhibitors have been applied in the treatment of respiratory disorders in clinical trials." (PMID 35720191, 2022). "In the treatment of pain and respiratory diseases, TRPA1 antagonists appear to be more pharmacologically relevant." (PMID 35630553, 2022). "Studies focusing specifically on TRPA1-blockade are needed, both for exploration of therapeutic horizons, as well as to clarify the functional role of TRPA1 in upper respiratory diseases." (PMID 33738577, 2021). "On the basis of genetic mutation, knockout animal studies and preclinical studies using small molecule antagonists, TRPA1 remains an attractive target for pain, dermatological diseases and respiratory diseases." (PMID 33810314, 2021). "The demand for TRPA1 antagonists has increased because of the important role of TRPA1 in pain, inflammation, itch and respiratory disease." (PMID 33810314, 2021). "This is also in line with several clinical trials in which TRPA1 antagonists are tested to treat respiratory diseases." (PMID 32503342, 2020). "The accumulating evidence supporting TRPA1 as an attractive target in respiratory disease has resulted in large number of small molecules patents." (PMID 27827953, 2016). "Several selective TRPA1 antagonists have been tested in animal models of respiratory disease and their performance is very promising." (PMID 27827953, 2016). "Till date, there is limited published literature showing efficacy of TRPA1 antagonists in respiratory diseases." (PMID 27827953, 2016). "Recent studies suggest that TRPA1 is involved in pain, itch, and respiratory diseases, and TRPA1 antagonists have been actively pursued as therapeutic agents." (PMID 25640188, 2015). "Activation of TRPA1 contributes to protective neuroimmune interactions to maintain homeostasis, thermotaxis, and modulation of lifespan, and TRPA1 is involved in some respiratory diseases when TRPA1 is activated by intense harmful signals such as LPS, stress and UV light." (PMID 39664395, 2024). "TRPA1 is widely distributed on C fibers and plays an important role in respiratory diseases." (PMID 35911969, 2022). "Based on our findings and those of others using genetic deletion, we suggest that pharmacological blockade of TRPA1 could provide therapeutic benefit in human respiratory disorders." (PMID 31969645, 2020). "Preclinical performance of TRPA1 antagonists in respiratory disease models is promising." (PMID 27827953, 2016). "TRPA1 is highly expressed on pulmonary innervation—an anatomically relevant region for respiratory diseases, and could be one of the major players in orchestration of airway inflammatory response." (PMID 27827953, 2016). "Recent studies have revealed its important functions in chronic pain mechanisms and its association with inflammatory diseases, neuralgia, vascular diseases, immune responses, and respiratory diseases, suggesting that TRPA1 may be an important target for the treatment of several diseases." (PMID 39273183, 2024).